IL6 (interleukin 6)
Diseases named in the same sentence as IL6 in open-access papers (continued):
Sharing a sentence is not in itself a finding about the gene and the disease.
insomnia (continued). "Patients with insomnia and poor sleep quality suffering from orofacial pain showed this IL-6 upregulation, thus demonstrating that the immune factor might play an important role in this interaction." (PMID 41459132, 2025). "Increasing evidence suggests that insomnia may increase the inflammatory cytokine interleukin-6 (IL-6) expression by enhancing nuclear factor-kappa B (NF-kB) activation and β-Adrenergic signaling." (PMID 38670978, 2024). "Importantly, however, we argue that the effect of IL6 trans signaling interpretation can be problematic, since our multivariable MR clearly showed that the effect of sIL6R on insomnia is confounded or mediated by CRP." (PMID 38511149, 2024). "In addition, treatment of sleep disorders such as insomnia can reverse the levels of inflammatory markers and reduce IL-6 and TNF levels to alleviate systemic inflammatory responses." (PMID 37872570, 2023). "However, when insomnia persists, the products of the inflammation response including IL-6 and cytokine such as CRP remain concentrated in the blood." (PMID 36361052, 2022). "There was also some evidence in IVW but not weighted median MR analysis for associations of (indirect) IL-6 signaling with sleep problems, but not with insomnia, suggesting potential association specificity to hypersomnia." (PMID 33079133, 2021). "All but one of the tested associations between insomnia symptom categories and sCD14, IL-6, and D-dimer were not significant." (PMID 33561176, 2021). "As is said before, IL-6 levels are elevated in insomnia and sleep deprivation." (PMID 33023629, 2020). "Moreover, the evidence suggests that individuals with insomnia had increased pro-inflammatory cytokines such as IL-6, nuclear factor-κB, and TNF-α." (PMID 31404954, 2019). "While human studies have found that IL-6 levels are increased in serum following sleep deprivation, sleep restriction and insomnia, it remains unclear whether salivary IL-6 levels are modified by sleep disruption." (PMID 23637783, 2013). "We hypothesized that insomnia symptoms would be associated with higher circulating levels of the monocyte activation marker soluble CD14 (sCD14), the inflammatory marker interleukin-6 (IL-6), and the coagulation marker D-dimer." (PMID 33561176, 2021). "Both preclinical and clinical investigations have consistently observed elevated peripheral blood levels of IL-6, IL-1β, and TNF-α in insomnia patients." (PMID 41310834, 2025). "One viewpoint suggests that elevated levels of pro-inflammatory cytokines can worsen insomnia, while exercise can help restore a stable sleep–wake cycle by improving TNF-α, IL-1β, IL-6, and other pro-inflammatory cytokines." (PMID 40115345, 2025). "This led to elevated levels of inflammatory cytokines such as IL-1β and IL-6, activating the HPA axis and increasing the secretion of CRH, ACTH, and CORT, ultimately triggering insomnia." (PMID 40507808, 2025). "Conversely, outcomes such as waist circumference, CRP, IL-6, TNF-α, QoL (quality of life), fatigue, pain, insomnia, physical functioning, and emotional functioning were rated as moderate quality due to small sample sizes." (PMID 40642165, 2025). "IL-6, IL-1β, and TNF-α are common inflammatory factors, and significantly higher IL-6 and TNF-α levels are reported in patients with insomnia than in healthy individuals, whereas decreasing their levels had a calming effect." (PMID 37670944, 2023). "Inflammatory state:Insomnia-(pw8b)-central nervous system-(pw25)-(pw66)-↑ghrelin:leptin-(pw67)-↑insulin resistance-(pw70)-↑angiotensin II-(pw88)-renin-(pw50)-↑TNF-α, IL-6-(pw41)-↑Inflammatory state." (PMID 35252372, 2022). "The levels of melatonin, TNFα, and IL-6 were correlated with the Insomnia Severity Index so that the higher the insomnia score, the higher the levels of TNF-α and IL-6 and the lower the melatonin levels." (PMID 33579032, 2021).
insomnia (continued). "From a pathophysiological standpoint, insomnia activates the hypothalamic-pituitary-adrenal (HPA) axis and disrupts circadian cortisol rhythms, thereby increasing systemic inflammation through elevated levels of cytokines such as IL-6 and TNF-α." (PMID 40756597, 2025). "When sleep deprivation occurs, IL-6 and TNF-α increase in the body, and when the body shows high levels of inflammation, it leads to a decrease in sleep duration and induces split sleep, which leads to sleep disturbances such as insomnia." (PMID 38502408, 2024). "The differences between IL-6 and IL-10 levels in women with and without insomnia were not significant." (PMID 37840785, 2023). "The potential correlation between the BDNF levels, interleukin-6 (IL-6), tumour necrosis factor-alpha (TNF-α), and depressive symptoms such as nine-item patient health questionnaire (PHQ-9) and Athens insomnia scale (AIS) were evaluated with multivariate logistic regression analysis." (PMID 31234814, 2019). "Recent studies provide laboratory based evidence that acupuncture affects the sleep-wake-up cycle by interfering with many levels of insomnia-related cytokines and neurotransmitters (such as 5-HT, NE, DA, GABA, Glu, IL-1, IL-6, TNF, and NO) which plays a role in sedative hypnosis and promotes sleep." (PMID 31341495, 2019). "There are evidences that both IL-6 and TNF-a are increased after chronic sleep deprivation, and IL-6 plasma levels are enhanced in patients with insomnia." (PMID 25926773, 2015). "The median IL-6 levels in women with and without AIS score-based insomnia were 10.65 pg./mL and 14.95 pg./mL, respectively, and the median IL-10 levels in those two groups were 0.99 pg./mL and 1.04 pg./mL, respectively." (PMID 37840785, 2023).
neuroblastoma (93 papers, 2009 to 2025). Neuroblastoma (NB) is the most common solid, extracranial childhood tumor. "Studies showed that VEGF, IL-6, and IL-10 receptor (IL-10R) in neuroblastoma were associated with poor outcomes." (PMID 33322408, 2020). "In other malignant diseases, such as Hodgkin’s lymphoma or neuroblastoma, high IL6 blood serum expression is associated with poor prognosis." (PMID 26215971, 2015). "High peripheral blood level of IL6 is associated with poor-outcome of neuroblastoma, and is believed to stimulate the invasion of osteoblastoma tumor cells to bone microenvironment." (PMID 25551100, 2014). "In clinical trials, zoledronic acid combined with conventional chemotherapy, decreases the production of IL6, which is associated with poor-outcome of neuroblastomas." (PMID 25551100, 2014). "Similarly, IL-6 plays a role in T cell differentiation and cytokine production and was associated with a favorable outcome in high-risk neuroblastoma." (PMID 36068918, 2023). "The presence of TAMs and high levels of specific chemokines and cytokines, including interleukin-6 (IL-6), is associated with lower survival rates in patients with several types of tumors, including neuroblastoma (NBL) for which the prognosis is poor in children with high-risk disease." (PMID 29207662, 2017). "The microenvironment of high-risk neuroblastoma tumors includes macrophages, IL-6, and TGFβ1." (PMID 23982484, 2013). "Furthermore, we found that high-risk primary neuroblastoma tumors contain CD68+ tumor-associated monocytes/macrophages (TAMs) producing IL-6 and that bone marrows with neuroblastoma metastases include CD33+ CD14+ monocytic cells, which also express IL-6." (PMID 23982484, 2013). "Our findings are corroborated by two recent publications in rodent models that showed that IL-6 + sIL-6R can elevate joint sensory neuron firing in vivo and in vitro, as well as elevate Socs3 and Csf1 in a mouse neuroblastoma cell line." (PMID 40373045, 2025). "In human cells, treatment of SH-5Y5Y neuroblastoma cells with corticosterone decreased autophagy function, which led to increased IL-6 and IL-10 production, although the mechanisms are unclear." (PMID 39639175, 2025). "On the other hand, CAFs derived from neuroblastomas have shown that IL-6 activates various signaling pathways, including STAT3, ERK1/2, and STAT1, in tumor cells." (PMID 38606999, 2024). "MSCs and CAF-MSCs harvested from neuroblastoma tumors protect human monocytes (MNs) from spontaneous apoptosis via an interleukin (IL)-6-dependent mechanism." (PMID 39156727, 2024). "In the scope of the study, vehicle control, DX and NP doses were applied individually and in combination to SH-SY5Y neuroblastoma cells, and IL-6, IL-6-R, Jak2, and Stat3 gene expressions were determined at the end of 48 hours." (PMID 39356934, 2024). "Gal‐3 binding protein secreted by neuroblastoma cells stimulates IL‐6 production in bone marrow mesenchymal stem cells via a Gal‐3BP/Gal‐3/Ras/MEK/ERK signaling pathway." (PMID 39230472, 2024). "Our findings that NA blocked oxidative stress, LD formation, and IL-6 expression in neuroblastoma cells were consistent with this earlier finding." (PMID 36985364, 2023). "In line with this, GSEA showed lower activity of inflammatory signaling (inflammatory response, IL-, IFN-, TNFα-, and IL6-JAK-STAT3 signaling) in Ewing sarcoma cDCs than in neuroblastoma cDCs, but higher oxidative phosphorylation." (PMID 37823774, 2023). "In vitro and in vivo studies have demonstrated that CCL2-attracted TAMs in neuroblastoma enhance IL-6 expression, promote tumor growth and inhibit apoptosis." (PMID 38087370, 2023). "The K vitamins, indeed, were able to reduce the inflammatory response via NF-kB signaling pathway inactivation, which, in turn, resulted in significantly suppressing the expression of IL-1β and IL-6 in neuroblastoma cells." (PMID 38201262, 2023).
neuroblastoma (continued). "With the exception of ID2, all the other immune genes (CD8a, IL2, IL7R, IL6, ID3, and CXCR3) were also highly expressed in low-risk neuroblastoma patients further confirming the significance of these immune genes in neuroblastoma cases with favorable outcomes." (PMID 36068918, 2023). "Upstream, TGF-β stimulated IL-6 production in neuroblastoma cells and MSC, contributing to the suppression of NK cell cytotoxic activity." (PMID 38087370, 2023). "Our previous studies showed that reactive oxygen species (ROS) and inflammatory cytokines, such as TNF-α, IL-1β, and IL-6, induced FtMt expression in the human neuroblastoma cell line IMR-32." (PMID 35008961, 2022). "Previous studies have shown elevated levels of IL-6 in various types of cancer (lung, mammary gland, colon, and neuroblastoma)." (PMID 33573284, 2021). "IL-6 in turn induced proliferation of neuroblastoma cells, creating a favorable microenvironment for progression of metastatic neuroblastoma." (PMID 34565385, 2021). "IL-6 produced by MSCs was reported to participate in promoting survival of neuroblastoma cells and bone metastasis." (PMID 33838662, 2021). "Intriguing, it has been proposed a functional role for LGALS3BP expressed at the surface of neuroblastoma-derived exosomes, that is the ability to induce the production of IL-6 in a RAS/MEK/ERK-dependent manner." (PMID 34565385, 2021). "In mouse and human neuroblastoma cells, TAMs are found to increase STAT3 activation in neuroblastoma cells, and up-regulates MYC oncogenes, a process associated with IL-6 independent expression." (PMID 33224886, 2020). "The results of this phase I trial suggest that this combination was well-tolerated and decreased osteoclast activity and serum IL-6 levels in patients with relapsed or refractory neuroblastoma." (PMID 32983125, 2020). "The cytokines IFN-γ, IL-2, IL-7, IL-12, IL-15, IL-18, IL-21, and IL-27, promoted neuroblastoma regression via enhancing the efficacy of effector cells, whereas VEGF, IL-6, and IL-10 induced neuroblastoma progression through their immunosuppressive activities." (PMID 33322408, 2020). "Previous studies showed that neuroblastoma EVs induced the production of pro-tumorigenic cytokines and chemokines such as IL-6, IL-8, VEGF, and CCL2 by MSCs." (PMID 33322408, 2020). "In the presence of soluble IL-6 receptor (sIL-6R), IL-6 effectively activated STAT3 in neuroblastoma and prevented drug-induced apoptosis in neuroblastoma in a STAT3-dependent manner." (PMID 32872659, 2020). "Transfection of miR-155 induced robust mRNA expression of IL-1β, IL-6, and IL-15 in neuroblastoma cells at 24 h after WNV NY99 infection." (PMID 31861621, 2019). "IL-6 and its bone destructive roles can be tied to certain cancers, including MM and neuroblastoma, both of which induce IL-6 secretion from the surrounding stroma resulting in bone loss through the NFκB pathway." (PMID 30671025, 2018). "In human neuroblastoma cell lines STAT3 mediates the inhibition of apoptosis by IL-6 and the up-regulation of BIRC5 and BCL2L1 by IL-6 two actions probably involved in the drug resistance of some human neuroblastomas." (PMID 28467792, 2017). "IL-6 secretion in MSCs was found to be stimulated by neuroblastoma cells within the bone marrow which in turn activated osteoclasts." (PMID 28148268, 2017). "IL-6, secreted by monocytes, and TGFβ1, secreted by neuroblastoma cells and monocytes, were shown to suppress IL-2 activation of NK cells." (PMID 26729169, 2015). "IL6 levels decrease with zoledronic acid combined with cyclophosphamide in pediatric patients with neuroblastoma." (PMID 25551100, 2014). "We also show that IL-6, similar to the neuroblastoma/monocyte CM, significantly suppresses release of IFNγ by IL-2-stimulated NK cells." (PMID 23982484, 2013).
neuroblastoma (continued). "As with experiments testing neuroblastoma/monocyte CM, we discovered that lenalidomide, at clinically achievable concentrations, prevented IL-6 suppression of IL-2-mediated activation of NK cell cytotoxicity, ADCC, and IFNγ secretion." (PMID 23982484, 2013). "IL-6, similar to the neuroblastoma/monocyte CM, significantly increased NK cell secretion of IL-6, whereas lenalidomide prevented this effect (data not shown)." (PMID 23982484, 2013). "Since the suppression of NK cell activation by neuroblastoma/monocyte CM was likely due to IL-6 and/or TGFβ1, we next tested these cytokines alone and with lenalidomide to determine the effects upon NK cell activation." (PMID 23982484, 2013). "Although the neuroblastoma/monocyte CM contained IL-6 and TGFβ1, these cytokines were increased further in cultures of NK cells and IL-2." (PMID 23982484, 2013). "CM from neuroblastoma/monocyte co-cultures contains IL-6 and TGFβ1 that suppress IL-2 activation of NK cell cytotoxicity and IFNγ secretion." (PMID 23982484, 2013). "Recombinant IL-6 and TGFβ1 were used at functionally effective doses to model the neuroblastoma/monocyte generated molecules to study the effects of these cytokines individually without or with lenalidomide upon NK cell activation." (PMID 23982484, 2013). "In summary, our study demonstrates that the microenvironmental milieu of neuroblastoma cells includes IL-6 and TGFβ1, which suppress IL-2 activation of NK cells for direct cytotoxicity, ADCC, and IFNγ secretion." (PMID 23982484, 2013). "Neuroblastoma cell/monocyte co-cultures generated CM that contained IL-6 and TGFβ1 and that suppressed IL-2 activation of NK cells for direct cytotoxicity, ADCC, and IFNγ secretion." (PMID 23982484, 2013). "We compared gene expression of neuroblastoma tumors and cell lines using a TLDA assay and found that tumors have higher expression of TAM-associated genes as well as of IL-6 and IL-10 than cell lines." (PMID 23982484, 2013). "To determine the role of IL-6 in human neuronal cells during flavivirus infection, we infected human neuroblastoma cells, SK-N-SH, with WNV NY99 or JEV Nakayama strain at the MOI of 0.1 and treated these infected cells with various concentrations of anti-IL-6 antibody." (PMID 38053527, 2023). "Finally, SH-SY5Y neuroblastoma cells treated with IL-6 (from 0.025 to 25 ng/mL) resisted the oxidative damage caused by hydrogen peroxide." (PMID 36769233, 2023). "In addition, in vitro studies on JEV-infected human neuroblastoma cells have shown impaired β-oxidation of long-chain fatty acids (PUFAs) and increased expression of interleukin 6 (IL-6) and tumor necrosis factor α (TNF-α)." (PMID 37775774, 2023). "Therefore, targeting the IL-6/TGF-β axis holds promise as a strategy to selectively deplete TAMs from the neuroblastoma TME." (PMID 38087370, 2023). "The ability of STVNA to reduce IL-6 levels was already displayed in neuroblastoma cells." (PMID 36145501, 2022). "Several neuroblastoma cells are capable of producing IL-6 spontaneously." (PMID 34539802, 2021). "In the first study, they identified and isolated LGALS3BP from serum-free conditioned medium of several neuroblastoma cells, and proved that it stimulated expression of IL-6 followed by an increase in Erk1/2 activation in human bone marrow stromal cells (BMSC) expressing its receptor Galectin-3." (PMID 34565385, 2021). "Similarly, our data demonstrated that transfection of miR-155 mimic induced robust mRNA expression of IL-1β, IL-6, and IL-15 in human neuroblastoma cells." (PMID 31861621, 2019). "DNA methylation status of CpG and non-CpG moieties in the 5′-flanking regions of the IL-1β and IL-6 genes has been studied by bisulphite treatment of genomic DNA purified from human neuroblastoma SK-N-BE cells, cultured for 24 h in control or 0.5 mM ALA supplemented medium." (PMID 28954414, 2017).